ENSG00000276232 (small Cajal body-specific RNA 10)
Gene: Long non-coding RNA gene on chromosome 12 (6,510,275 to 6,510,522, forward strand). Ensembl gene ENSG00000276232.
Gene Ontology:
Biological process: RNA processing
Cellular component: nucleolus
Diseases named in the same sentence as ENSG00000276232 in open-access papers:
ENSG00000276232 is named in the same sentence as 1 disease in open-access papers, as found by Europe PMC text mining. Sharing a sentence is not in itself a finding about the gene and the disease. The quoted sentences say what the papers report.
Hepatic fibrosis (1 paper, 2022). The presence of excessive fibrous connective tissue in the liver. "Previously, we identified lncRNA Small Cajal body-specific RNA 10 (SCARNA10) is up-regulated in the serum and liver tissue samples from patients with advanced hepatic fibrosis, which promotes liver fibrosis both in vitro and in vivo through inducing HCs apoptosis and HSCs activation." (PMID 35443674, 2022).